ELOVL4 (ELOVL fatty acid elongase 4)
Diseases named in the same sentence as ELOVL4 in open-access papers (continued):
Sharing a sentence is not in itself a finding about the gene and the disease.
dermatitis (2 papers, 2019 to 2023). An inflammatory process affecting the skin. "In the present study, the expression of ELOVL1 and ELOVL4 was also downregulated in FAg-induced AD-like dermatitis, and the relative amount of CERs with long-chain FAs, C24-CER[NS] and C26-CER[NS], consistently decreased." (PMID 30838224, 2019). "In contrast to FAg-induced dermatitis, the expression level of ELOVL4 remained unchanged in IMQ-induced dermatitis." (PMID 30838224, 2019). "The expression of ELOVL4 substantially decreased by 76.2 ± 9.6% in FAg-induced dermatitis compared with that in control mouse skin, and the expression of the other ELOVL isozymes except for ELOVL3 also significantly decreased, with the highest inhibition in ELOVL6." (PMID 30838224, 2019).
Parkinsonism (2 papers, 2020 to 2026). Characteristic neurologic anomaly resulting from degeneration of dopamine-generating cells in the substantia nigra, a region of the midbrain, characterized clinically by shaking, rigidity, slowness of movement and difficulty with walking and gait. "One patient with an ELOVL4 variant exhibited skin changes, a typical symptom of ELOVL4 SCA, whereas the other ELOVL4 SCA patient had no skin changes and exhibited mild parkinsonism and calcification in the globus pallidus and dentate nucleus." (PMID 40940404, 2026).
autosomal dominant cerebellar ataxia (1 paper, 2023). A clinically and genetically heterogeneous group of neurodegenerative diseases characterized by a slowly progressive ataxia of gait, stance and limbs, dysarthria and/or oculomotor disorder, due to cerebellar degeneration in the absence of coexisting diseases. "Alongside ELOVL5, ELOVL4 is currently the only other elongase involved in an autosomal dominant cerebellar ataxia: SCA34." (PMID 37199746, 2023).
brain malformation (1 paper, 2024). "ELOVL4 is expressed in neurogenic regions of the developing brain, is implicated in cell cycle regulation, and ELOVL4 mutations that cause neuroichthyosis lead to developmental brain malformation, suggesting that aberrant neuron generation due to ELOVL4 mutations might contribute to SCA34." (PMID 38850484, 2024).
cerebellar degeneration (1 paper, 2025). Degeneration of the cerebellum. "Genetic analyses confirmed the involvement of ELOVL4-related disruptions in long-chain fatty acid biosynthesis, offering insight into the molecular underpinnings of cerebellar degeneration in SCA34." (PMID 41445982, 2025).
Chanarin-Dorfman syndrome (1 paper, 2013). "Accordingly, loss-of-function of enzymes involved in acylceramide metabolism result in cutaneous barrier abnormalities such as those found in human diseases and corresponding mouse models like ELOVL4-deficiency (MIM 614457) or Chanarin-Dorfman syndrome (MIM 275630)." (PMID 23754960, 2013).
chronic pancreatitis (1 paper, 2012). A chronic inflammatory process causing damage and fibrosis of the pancreatic parenchyma. "They found that ELOVL4 (a gene codifing the protein for the elongation of very-long-chain fatty acids 4-like, responsible for the biosynthesis of fatty acids) and CALCR (gene responsible for calcitonine receptor) were increased both in neuroendocrine tumors and chronic pancreatitis." (PMID 23021468, 2012).
colorectal adenocarcinoma (1 paper, 2023). The most common type of colorectal carcinoma. "Changes in the expression levels of ELOVL4 and ELOVL6 observed in our in vitro model of colorectal adenocarcinoma corresponded with changes observed in patients’ CRC tissue." (PMID 38139442, 2023).
cone dystrophy (1 paper, 2024). An inherited ocular disorder characterized by the loss of cone cells, the photoreceptors responsible for both central and color vision. "However, more time-course experiments, possibly involving electroretinograms and optokinetic and optomotor response tests—throughout the life span of the fish—from larvae to adulthood can be used to determine if Elovl4 dysfunction results in primarily a rod or cone dystrophy, or both." (PMID 38342437, 2024).
diabetic retinopathy (1 paper, 2014). "Our previous study demonstrated that decreased expression levels of retinal fatty acid Elongases Elovl2, Elovl4 and Elovl6 play an important role in the pathogenesis of diabetic retinopathy." (PMID 24736612, 2014). "We previously showed that fatty acid elongases Elovl2 and Elovl4 are reduced in diabetic retinopathy, thus, we examined their daily expression in the retina and liver." (PMID 24736612, 2014).
Dyschromatopsia (1 paper, 2021). A form of colorblindness in which only two of the three fundamental colors can be distinguished due to a lack of one of the retinal cone pigments. "Indeed, only a minority of patients of the ABCA4 and ELOVL4 cohorts reported photophobia, respectively 44% and 29%, and dyschromatopsia, respectively 11.11% and 14.29%." (PMID 34073554, 2021).
glioma (1 paper, 2022). A benign or malignant brain and spinal cord tumor that arises from glial cells (astrocytes, oligodendrocytes, ependymal cells). "According to the available studies, the expression level of ELOVL4 does not affect the prognosis of patients with GBM or glioma." (PMID 36291290, 2022).
Hepatitis (1 paper, 2018). Inflammation of the liver. "The decreased levels of PUFA in hepatitis patients in comparison to controls, which specifies the reduced activities of ELOVL2, ELOVL4 and ELOVL5 enzymes." (PMID 29506525, 2018).
Leber congenital amaurosis (1 paper, 2025). Leber congenital amaurosis (LCA) is a retinal dystrophy defined by blindness and responses to electrophysiological stimulation (Ganzfeld electroretinogram (ERG)) below threshold, associated with severe visual impairment within the first year of life. "The current patient also manifested variants of unknown significance in CRB1 and ELOVL4, genes associated with Leber congenital amaurosis and autosomal dominant Stargardt macular degeneration, respectively." (PMID 40747364, 2025).
melanoma (1 paper, 2024). A malignant, usually aggressive tumor composed of atypical, neoplastic melanocytes. "This suggests a relatively minor impact of IRF6 and ELOVL4 in melanoma, further emphasizing the context-dependent role of RIPK4 in both non-melanoma and melanoma skin cancers." (PMID 38656555, 2024).
Obesity (1 paper, 2020). Accumulation of substantial excess body fat. "Caloric restriction for 3 and 6 months significantly attenuated the increased expression levels of ELOVL4 in the obesity group, while a significant reduction of IL-33 expression levels was observed in the obese patients with a 6-month period of caloric restriction treatment." (PMID 32581837, 2020).
retinitis pigmentosa (1 paper, 2020). Retinitis pigmentosa (RP) is an inherited retinal dystrophy leading to progressive loss of the photoreceptors and retinal pigment epithelium and resulting in blindness usually after several decades. "The novel I171T ELOVL4 mutation that causes SCA accompanied by retinitis pigmentosa in some patients would be predicted to impair synthesis of VLC-SFA and also VLC-PUFA to some degree." (PMID 32780351, 2020).
skin changes (1 paper, 2026). "Notably, a previously reported Japanese family with an ELOVL4 SCA variant also did not exhibit skin changes, suggesting that Japanese patients are less likely to develop skin lesions than European patients." (PMID 40940404, 2026). "Previously reported cases of ELOVL4 SCA presented with skin changes in childhood; however, Patient 2 did not exhibit any skin abnormalities." (PMID 40940404, 2026).
tumor (8 papers, 2022 to 2025). "Next, we tested whether forced expression of Elovl4 could rescue the tumor suppression in Ripk4-deficient skin." (PMID 36765696, 2023). "Importantly, overexpression of Elovl4 suppressed tumor growth of Ripk4-deficient keratinocytes." (PMID 36765696, 2023). "Together, these data demonstrate that Elovl4 is not only essential for tumor suppression, but also sufficient to reduce SCC development in Ripk4-deficient, Pik3caH1047R-mutant skin." (PMID 36765696, 2023). "In the enhancing tumor region relative to the peritumoral area, the ELOVL4 expression was significantly higher (p = 0.02)." (PMID 36291290, 2022). "In addition, IHC results showed that tumours dissected from the sh-NC group exhibited higher ELOVL4 staining than those dissected from the sh-ELOVL4 group." (PMID 38817874, 2024). "Here, we describe an additional tumor suppressive feature of RIPK4 through upregulation of ELOVL4." (PMID 36765696, 2023). "Importantly, expression of Elovl4 drastically reduced tumor burden as well as tumor multiplicity while increasing latency of SCC formation in Ripk4-deficient, Pik3caH1047R-mutant skin." (PMID 36765696, 2023). "The ELOVL4 expression was elevated in the GBM tumor in the women." (PMID 36291290, 2022). "The ELOVL4 expression in the peritumoral area was positively correlated with the tumor core." (PMID 36291290, 2022). "Additionally, the ELOVL1 expression in the tumor core was positively correlated with ELOVL4, ELOVL5, ELOVL6, and ELOVL7 expressions." (PMID 36291290, 2022). "In addition, ELOVL4 may be a potential therapeutic target for GC, and the molecular mechanism regulating the malignant biological behaviour of tumour cells deserves further investigation." (PMID 38817874, 2024). "These molecular events trigger the expression of ELOVL4, a fatty acid elongase, which then suppresses the SCC tumor formation." (PMID 36765696, 2023). "This study examines the expression of elongases ELOVL1, ELOVL2, ELOVL3, ELOVL4, ELOVL5, ELOVL6, and ELOVL7 in GBM tumor samples from 28 patients (16 men and 12 women), using a quantitative real-time polymerase chain reaction (qRT-PCR)." (PMID 36291290, 2022). "There was a positive correlation between ELOVL4, ELOVL5, ELOVL6, and ELOVL7 expressions in the GBM tumor." (PMID 36291290, 2022). "To further rule out any confounding effects of the sgRNA library as well as off-targeting effects, we transduced Pik3caH1047R;LSL-Cas9-GFP mice with an independent Elovl4 sgRNA, which corroborated our findings and established Elovl4 as a novel SCC tumor suppressor." (PMID 36765696, 2023). "Although the expression of ELOVL1 was not statistically significant in para-tumor tissue compared to distant tissue, ELOVL4 catalyzes the synthesis of very long-chain fatty acids, and expression of this enzyme was also increased in the adjacent thyroid tissues with cancer examined." (PMID 39145825, 2025). "Importantly, our analysis revealed a statistically significant negative correlation between EC stage and ELOVL4 expression, indicating that ELOVL4 expression decreases with advancing tumor stage." (PMID 40244177, 2025). "Furthermore, the significant negative correlation between ELOVL4 expression and tumor stage suggests that this elongase plays a role in early-stage EC, and its downregulation could contribute to disease progression." (PMID 40244177, 2025). "In the tumor core, the expression of ELOVL3 had a negative correlation with body weight and BMI, while in the peritumoral area, there was a negative correlation between the ELOVL2 expression and height and a negative correlation between the ELOVL4 expression and cigarette pack-years." (PMID 36291290, 2022).
cancer (5 papers, 2020 to 2025). A tumor composed of atypical neoplastic, often pleomorphic cells that invade other tissues. "Through gene profiling and targeted CRISPR screening approaches in mouse models of cancer, we identified ELOVL4, (elongation of very-long-chain fatty acid-4) as a downstream target of RIPK4." (PMID 36765696, 2023). "Except ELOVL4, mRNA levels for all enzymes involved in the synthesis of longer and more desaturated PUFAs (from 18:2 n-6 to 18:3 n-3) turned out to be significantly higher in cancer tissues than in normal mucosa." (PMID 32029824, 2020). "The use of the siRNAs for ELOVL4 and ELOVL6 reduced cancer cell proliferation and migration rates." (PMID 38139442, 2023). "The mRNA levels of ELOVL4, ELOVL5 and FADS2 were increased in cultured cancer cells comparing to normal colon cells, but we did not detected the expression of ELOVL2 and FADS1 in these cells." (PMID 32029824, 2020). "The mRNA levels of ELOVL4 and 5, as well as FADS2 were higher in cancer cells than in normal colon cells, but we did not detected the expression of ELOVL2 and FADS1 in these cells." (PMID 32029824, 2020).
neurodegenerative disease (5 papers, 2017 to 2024). A disorder of the central nervous system characterized by gradual and progressive loss of neural tissue and neurologic function. "However, mutations in ELOVL4 cause neurodevelopmental or neurodegenerative diseases that vary according to the mutation and inheritance pattern." (PMID 28507511, 2017). "Despite the importance of VLCFA-lipids and ELOVL4 in neurological processes, very little is known about VLCFA-lipids/ELOVL4 in neurodegenerative diseases." (PMID 34725421, 2021). "Understanding the function of ELOVL4 and its VLC-SFA and VLC-PUFA products will advance our understanding of basic mechanisms in neural signaling and has potential for developing novel therapies for seizure and neurodegenerative diseases." (PMID 31616255, 2019).
infection (4 papers, 2017 to 2025). The state of being infected such as from the introduction of a foreign agent such as serum, vaccine, antigenic substance or organism. "FADS2- and ELOVL4-knockdown cells were infected with a high multiplicity of infection (MOI) and internalized DENV viral RNA (vRNA) was quantified at 4 hpi." (PMID 39863099, 2025). "Following the methodology described in Section 2.3, we identified three genes: IFIT1 (infection-dependent), IFIT2 (infection-dependent), and ELOVL4 (time-dependent), using GLMQL-RMAS as predictors for multinomial logistic regression." (PMID 38655085, 2024). "We also observed that ELOVL4 expression slightly but gradually increased during infection." (PMID 39863099, 2025). "While ELOVL7 was activated already at 6 h of infection, both ELOVL4 and ELOVL6 displayed a delayed response (activated at 16 h of infection)." (PMID 28993767, 2017). "To this end, we transduced the surface ectoderm of Ripk4fl/fl; Pik3caH1047R; LSL-GFP embryos with lentiviral Cre-constructs expressing either Elovl4 or tdTomato as a negative control at clonal infection levels (>10%)." (PMID 36765696, 2023). "Of note, the knockdown of ELOVL4 was cytotoxic for HMC3 cells (data not shown), thus we were not able to use the cells for infection experiments." (PMID 39863099, 2025). "In contrast, while the knockdown of ELOVL4 did not alter DENV copy numbers, it slightly decreased levels of intracellular viral proteins at 72 hpi, suggesting reduced translation or a delayed course of infection compared to shNT cells." (PMID 39863099, 2025).
neurological disease (2 papers, 2017 to 2019). "To date, nine different mutations in the human ELOVL4 gene have been identified that cause neurological disorders." (PMID 28507511, 2017). "Mutations in either ELOVL4 or ELOVL5 cause neurological disease in humans." (PMID 31616255, 2019). "Distinct sets of mutations in ELOVL4 cause three different neurological diseases in humans." (PMID 31616255, 2019). "In particular, we will focus on ELOVL4 and the role of its Very Long Chain-Saturated Fatty Acids (VLC-SFA) and Very Long Chain-PolyUnsaturated Fatty Acids (VLC-PUFA) products in neurological disease, synaptic transmission, and neuronal survival in the CNS." (PMID 31616255, 2019).
ELOVL4 also shares sentences with these, for which no sentence is quoted: skin disorder (5 papers); squamous cell carcinoma (4); Retinal dystrophy (3); age-related macular degeneration (2); Atrophy (2); autosomal recessive congenital ichthyosis (2); cerebellar ataxia (2); epilepsy (2); -phosphoglycerate dehydrogenase deficiency (1); 3-methylglutaconyl-CoA hydratase deficiency (1); abetalipoproteinemia (1); age (1); Anxiety (1); atopic dermatitis (1); autosomal dominant disease (1); bladder cancer (1); Blindness (1); cone-rod dystrophy (1); congenital ichthyosis (1); coproporphyria (1); dementia (1); developmental delay (1); endometriosis (1); erythrokeratoderma (1); esophagus cancer (1); Failure to thrive (1); frontotemporal dementia (1); Gait ataxia (1); glioblastoma multiforme (1); Hypertonia (1).
A further 18 diseases each share a sentence with ELOVL4 in 1 paper.